IL10 (interleukin 10)
Diseases named in the same sentence as IL10 in open-access papers (continued):
Sharing a sentence is not in itself a finding about the gene and the disease.
infection (continued). "The increased expression of IL-10 in fatal filovirus infections may be a concerted effort to dampen the overwhelming pro-inflammatory response but may exacerbate the deficiencies observed in adaptive immune response to infection." (PMID 26512687, 2015). "These parasites bias the immune response toward Th2 and/or a regulatory environment associated with high levels of IL-4, IL-13, IL-9, IL-5, and IL-10; also, infection with helminths compromises immunity to other unrelated infections and may also affect the efficacy of vaccines." (PMID 26090422, 2015). "Although such findings provide insight into genetic predispositions that could determine the outcome of infection, the analysis performed in our current study demonstrated that all infected patients produced more IL-10 upon classical T cell activation or filarial-specific re-stimulation." (PMID 24587458, 2014). "Furthermore, sustained expression of IL-10, mainly by resident glial cells during early infection, might limit the extent of damage caused by an unwanted immune response in the brain." (PMID 25391297, 2014). "Besides an extracellular or extrinsic role of enhancing antibodies, ADE may also enhance infection intrinsically by regulating the production of inflammatory-associated cytokines, such as IL-6, IL-10, IL-12, TNF-α and IFN-γ." (PMID 25329914, 2014). "The immunosuppressive IL-10 has long been associated to visceral disease pathogenesis, being not only important in the establishment of infection but also during parasite persistence through the direct inhibition of Th1 cell development, preventing the resolution of the infection." (PMID 25368612, 2014). "Furthermore, DC play a prominent role in orchestrating the induction of immune responses against pathogens and, thus, might contribute to susceptibility to infection by IL-10 secretion." (PMID 23825956, 2013). "Taken together, these data demonstrate that T cell-derived IL-10 production during early B. abortus infection is crucial for the development of the chronic disease and morbidity caused by B. abortus, and limits the production of the pro-inflammatory response necessary to control the infection." (PMID 23818855, 2013). "In our study, similar result was showed that the apoptosis of BeWo cells and primary trophoblast cells were positively with the up-regulation of HLA-G expression; meanwhile, IL-10 treatment could cause a decrease of HLA-G in early stage of infection with T. gondii." (PMID 23418570, 2013). "In infections in which the control of the infectious agent is mediated by a strong Th1 response, such as infection with Listeria monocytogenes, Trypanosoma cruzi and respiratory influenza virus, the concomitant presence of IL-10 may prevent the tissue damage associated with Th1 responses." (PMID 23824716, 2013). "Moreover, these IL-10−/− mice are extremely susceptible to infection-induced immunopathology." (PMID 22681958, 2012). "Elevated levels of IL-10 may have important effects in the modulation of inflammatory responses to the parasite that prevent potentially damaging pathology but increase susceptibility to infection." (PMID 22848773, 2012). "Further, the unchanged systemic concentrations of IL-6, KC, and IL-10 do not rule out that other important mediators in the posttraumatic inflammatory cascade may be altered by inhalative IL-10 and thereby the susceptibility to infection may again be increased." (PMID 22046081, 2012). "On the contrary, low CD4 counts (a marker of immune-compromise) have been associated with elevated IL-10 levels during acute infection with Bartonella, a cytokine milieu that may allow an acute infection to persist especially given the anti-inflammatory nature of IL-10." (PMID 22162717, 2012).
infection (continued). "The aim of our present study was to measure the levels of TREM-1 and HLA-DR on monocytes, and the serum concentrations of IL-6 and IL-10 in patients with AP, and to determine whether these markers can be used for early identification of patients at high risk of developing severe AP or infection." (PMID 19442309, 2009). "Thus, notwithstanding further effects of prior exposure to mosquitoes, heightened IL-10 production associated with an anti-mosquito immune response may account for the altered course of infection." (PMID 18000543, 2007). "Males had higher overall levels of pro-inflammatory cytokines and IL-10 and lower levels of IL-27, which are known to inhibit the protective responses to Salmonella infection." (PMID 41810958, 2026). "Functional analysis showed that LAG3-expressing CD4+CD44+ T cells secreted elevated levels of interleukin-4 (IL-4) and IL-10 at 2 and 4 weeks post-infection." (PMID 41680821, 2026). "In contrast, lethal infections are often marked by inadequate or poorly timed IL‐10 responses, contributing to unchecked inflammation and mortality." (PMID 41461395, 2026). "While IL-10-producing Tfh expanded during infection, IL-9-producing cells and Th17 cells expanded mainly after treatment." (PMID 41823215, 2026). "Our data showed that animals from the Lb/HSP65 group significantly increased IL‐10 production from 6 to 10 weeks after infection compared to the Lb or Lb/Ø group." (PMID 40745935, 2026). "Mice from Lb/HSP65 showed a higher production of IL‐10 than IFN‐γ during 6 to 8 weeks post‐infection." (PMID 40745935, 2026). "During the early stages of infection, F. hepatica induces a mixed Th1/Th2 response characterized by up‐regulating IL‐4, IL‐10, and TGF‐b." (PMID 41503693, 2026). "This study aimed to describe the cytokine responses (IL-2, IL-6, IL-10, TNF-α, IFN-γ) associated with each infection." (PMID 41547724, 2026). "Conversely, the production of anti‐inflammatory cytokines such as IL‐4 and IL‐10 is high at the beginning of the infection." (PMID 41500977, 2026). "In severe infection, mRNAs of IL‐4, IL‐5, IL‐6, IL‐10 and IL‐13 highly expressed compared to the non‐infected control, but the interferon‐ (INF)‐γ expression remained unaltered." (PMID 41503693, 2026). "These CD8+ cells displayed decreased IL-4 and TNF-αexpression during infection, but an increased level of productionof IL-10." (PMID 41365681, 2026). "Elevated levels of IL‐10 during the initial phase of the infection have been correlated with increased disease severity, as its potent anti‐inflammatory properties interfere with the host antiviral response." (PMID 41488232, 2026). "Our data show that neutrophils and Ly6C+ monocytes are major sources of lung IL-10 during the first 48 h post-infection, a cytokine that is required for host survival, host defense, and to reduce lung inflammation and injury." (PMID 41733356, 2026). "The overall IL-10 production by T cells is important to protect against excessive inflammation and damage during the peak of infection for Leishmania mexicana and L. major." (PMID 40831564, 2025). "P. salmonis triggers the overexpression of il10 in the rainbow trout macrophage-like cell line (RTS11) during the early stages of infection." (PMID 41334221, 2025). "In subtype C, we found that the changes in the biomarker profiles post infection compared to pre-infection were due to increases in TNFα, IL-10, IL-6, IL-13, IL-5, IFNγ, IL-12, IL-4, ITAC, IL-17α, and IL-23." (PMID 40862133, 2025). "We conclude from these analyses that cmvIL-10 is the most expressed HCMV IL-10 transcript during early reactivation to productive infection, while LAcmvIL-10 seems to generally be expressed at much lower levels than cmvIL-10." (PMID 40284944, 2025). "STAT3—primarily activated by IL-10—is essential for effector CD8+ T cell differentiation during acute infection." (PMID 41156600, 2025).
infection (continued). "Together, these data suggest that HTLV-1A/CoI-L infection results in higher and persistent inflammation at the expense of IL-10-mediated pro-resolution myeloid populations in blood and BAL compared with HTLV-1A." (PMID 41006234, 2025). "As the infection progresses, the host responses turn into anti-inflammatory or anti-disease responses by producing IL-10 and induction of regulatory subsets of innate immune cells (immunoregulation)." (PMID 39847577, 2025). "This indicates that the decrease in CD73 expression on dMφ after infection regulates the expression of Arg-1 and IL-10 by influencing the binding of Ado to A2AR." (PMID 39994736, 2025). "Upon Ld-infection, IL-12 mRNA expression remained unaltered, whereas IL-10 mRNA was markedly upregulated by 2.99-fold (p ≤ 0.01)." (PMID 41339683, 2025). "This complexity needs a comprehensive understanding of IL-10’s role across various infections and patient populations." (PMID 41156600, 2025). "Of note, not only during AT, but also during infection with other trypanosomatids, IL-10 has been found to play a regulatory role." (PMID 41471231, 2025). "Flow cytometry analysis indicated some changes in the phenotype of IL10+ B cells in the spleen after infection, which likely reflects both activation of pre-existing IL10+ cells and induction of new IL10+ B cell populations." (PMID 41191641, 2025). "In mouse sera post-PCV2 infection also showed elevated levels of IL-6, IL-8 IL-10, TNF-α, and MCP-1 (p < 0.05 or p < 0.01)." (PMID 39968105, 2025). "In immunologically naïve animals, virulent ASFV challenge can produce increased serum IL-10 during late-stage infection immediately prior to death, though this is inconsistently observed." (PMID 41156603, 2025). "Our observation that specific cytokines, particularly IL-10 and IL-12p70, remained elevated for up to 10 weeks post-infection suggests that the immune perturbation induced by SARS-CoV-2 extends far beyond the acute phase of illness." (PMID 41157586, 2025). "In the experimental infection model of C57BL/6 mice with L. (L.)major, parasite persistence in the host is associated with a population of regulatory T cells through IL-10-dependent or independent mechanisms." (PMID 41017914, 2025). "In contrast, IL-6 and IL-10 demonstrated superior discriminative power, with AUC values exceeding 0.8 for predicting severe infection." (PMID 40647525, 2025). "Conversely, the anti-inflammatory cytokine IL10 was reduced in NHBEA/A cultures after infection with both viruses." (PMID 40627391, 2025). "In contrast, IL-10 initiates suppressive mechanisms that downregulate the inflammatory response and reduce pathological tissue damage during infection." (PMID 40627782, 2025). "This pharmacological blockade resulted in a similar phenotype, with impaired erythropoiesis in both the BM and spleen, validating that IL-10 signaling is involved in sustaining RBC production during infection." (PMID 41471231, 2025). "And the ITA infection group showed more significant upregulation of cytokines (IL-4, IL-10, TNF-α, IFN-γ), histopathological damage to lungs, and higher bacterial load and mortality than the IN and ITI groups." (PMID 40723822, 2025). "Our findings demonstrate that tofacitinib treatment early during infection ameliorates intestinal inflammation driven by human mucosal pathogen C. jejuni in both IL-10 KO mice and in humanized mice with intact IL-10 signaling." (PMID 40614970, 2025). "In contrast to pro-inflammatory factors, anti-inflammatory cytokines such as TGF-β and IL-10 exhibited a gradual decline in expression during the initial stages of infection, with a recovery observed at 15 dpi." (PMID 39799330, 2025). "At 35 days after infection, during the chronic phase, we observed an increase in the Th2 cytokines IL-6 and IL-10 in infected mice." (PMID 39899646, 2025).
infection (continued). "Systemically, MCP-1 recruits monocytes and dendritic cells to infection sites, while IL-4/IL-13 drives B-cell class switching, and IL-10/TGF-β modulate inflammation to prevent tissue damage." (PMID 40668875, 2025). "Elevated IL-10 expression in AQP-RE-infected mice during early infection suggests enhanced immune regulation in response to lower virulence." (PMID 41394106, 2025). "IL-10, a regulatory cytokine produced by Th2 cells, was lower in the A group at 16 dpi and higher in the AS group but only at the beginning of infection." (PMID 40586570, 2025). "The Ld-infection results in increased secretion of IL-12 (44.53 ± 14.43 pg/mL; p ≤ 0.05) and IL-10 (114.10 ± 12.11 pg/mL; p ≤ 0.01)." (PMID 41339683, 2025). "In contrast, IL-10 levels were also elevated, indicating a potential regulatory role in the immune response during infection." (PMID 41152306, 2025). "To investigate the infection efficiency and expression levels of IL-4, IL-10, and IL-13 in modified MSCs, we examined their fluorescence and secretion levels." (PMID 40038782, 2025). "Herbs that possess anti-coccidial properties due to their tannin content can lower inflammatory cytokines like TNF-α in peripheral serum and boost the body’s defenses against infection (IL-10 and IgA)." (PMID 39762829, 2025). "At 5 days post-infection (dpi), IL-10 expression was significantly elevated in Groups 2 and 3 compared to the other groups (p < 0.01)." (PMID 40909923, 2025). "At 3 days post-infection, BALB/c mice had elevated levels of inflammatory cytokines IFNγ and GZMB and elevated levels of the anti-inflammatory cytokine IL-10 at 6 days post-infection." (PMID 40733664, 2025). "Persisting low-grade infection is characterized by higher frequencies of IL-10-secreting CD4+ effector memory T cells, which agrees with our findings in the severely ill patients in both the acute and convalescent phases." (PMID 40766325, 2025). "ELISA results indicated that in the rCsCP1 immunized group, IL-10 levels surged over 10-fold (11.73 ± 1.97)by the first week post-infection, compared to control groups, and remained elevated at the second week." (PMID 40248698, 2025). "Lastly, there was a significant decrease in circulating IL-10 levels post M.tb HN878 infection in serum of the ID93+EmT4TM immunized group." (PMID 40285479, 2025). "Conversely, reductions in the immunoregulatory cytokine IL-10 were seen on both the 2nd and 7th days after infection." (PMID 41471915, 2025). "We had previously demonstrated that infection with B. pertussis induces IL‐10‐secreting CD4+ Treg cells." (PMID 40629997, 2025). "In the pig ASFV trial, levels of pro-inflammatory cytokines, including IL-6 and IL-8 increased from 3 days p.i., while IL-10 was only detected at the terminal stages of the infection together with a second peak in pro-inflammatory cytokine levels." (PMID 40533814, 2025). "Serum IL-10 level was significantly higher in EV-71-infected WT mice than in PLG-KO mice at 2 days post-infection." (PMID 40377310, 2025). "Because inducing the secretion of M2-associated cytokines by microbes has been described as a common mechanism to suppress inflammatory responses, we tested levels of secreted IL-10, an immunosuppressive cytokine, between infection conditions." (PMID 39975246, 2025). "At 24 h post-infection, the immune-modulatory cytokine IL-10 was exclusively detected in placental explants." (PMID 41450943, 2025). "The anti-inflammatory cytokine IL-10 was significantly upregulated following infection, reaching its peak at 12 dpi, after which its expression gradually decreased but remained elevated through 21 dpi." (PMID 41295722, 2025). "In the rCsCP3 immunized group, IFN-γ, IL-2, and IL-10 were elevated from the first week post-infection (P < 0.01), with IL-4 levels increasing in the second week." (PMID 40248698, 2025).
infection (continued). "Infection with the psarAI168R mutant strain also leads to significantly lower production of IL-10 compared to wild type, whereas infection with the psarA:gp130R168I mutant leads to significantly increased IL-10 compared to the psarA:gp130 strain." (PMID 40188438, 2025). "After infection, the expression levels of Il10, Tnfa, Il1b and Il6 increased significantly in both young and aged mice at 4 dpi, peaking at 7 dpi." (PMID 41145556, 2025). "Hence, IL-10 deficiency may result in an impaired BFU/CFU differentiation during infection." (PMID 41471231, 2025). "Specifically, certain subsets can secrete anti-inflammatory cytokines such as IL-10 and IL-35, thereby modulating immune responses throughout infection." (PMID 41246314, 2025). "The total IL-10 mean in the group of virus-infected children was also significantly higher than that of the group of children with an undetected infection: 12.6 (8.4–18.3) vs. 9.1 (6.4–10.5) (p < 0.001)." (PMID 40430746, 2025). "ISG15−/− mice exhibited exacerbated inflammatory pathology and low levels of IL-10 in the FGT at the later stage of infection, suggesting that ISG15-induced IL-10 limits pathology during infection." (PMID 40627782, 2025). "We show an inverse correlation between the decrease in atRA and the increase in inflammatory cytokines IL‐1β, IL‐6, IL‐10 and IL‐12 in lung tissue during infection." (PMID 40031928, 2025). "Since anti-IL-10R antibody treated WT mice phenocopied their IL10-KO counterparts during infection, all further experiments were performed using the pharmacological approach with the anti-IL-10R blocking antibody." (PMID 41471231, 2025). "While IL-10 normally helps regulate immune responses to prevent tissue damage, its dysregulation in sepsis exacerbates immunosuppression, further impairing infection control." (PMID 40265185, 2025). "In this study, we observed that mice lacking ISG15 exhibited uterine horn pathology and lower levels of IL-10 in FGT tissue at a later stage of infection." (PMID 40627782, 2025). "Following infection, the phenotype of IL10+ B cells was largely maintained in the peritoneum but showed dynamic changes in the spleen, including increased IL10 expression and further IgM downmodulation consistent with B cell activation." (PMID 41191641, 2025). "We didnot observe any changes in IL-2, IL-4, or IL-10 levels resulting fromthe infection; however, ravuconazole-treated mice presented higherlevels of IL-4, and combination therapy significantly increased theIL-4 and IL-10 compared to untreated infected mice." (PMID 40488037, 2025). "This dampened immune response was corroborated in the serum levels of the cytokines IL-6 and IL-10 measured in both mouse strains, with C3 KO mice producing less of both cytokines at peak infection (day 3 post-infection) with Ig::Tn compared to WT B6 mice." (PMID 40586810, 2025). "This response is characterized by the production of cytokines such as IL-4, IL-5, IL-6, IL-10, and IL-13, which deactivate infected macrophages and allow parasite dissemination at infection sites and internal organs." (PMID 40391226, 2025). "The production of key cytokines (IL‐1β, IL‐18, IL‐6, IL‐10, IL‐12) and nitric oxide (NO) was quantified at 24 to 96 h post‐infection." (PMID 40940710, 2025). "Treatment of secondary abiotic IL-10−/− mice with synthetic 25-OH-cholecalciferol starting 4 days before infection resulted in less frequent C. jejuni-induced diarrhea and counteracted intestinal cell damage." (PMID 40395728, 2025). "During the immune response, the Th1 cytokines, IFN-γ, IL-1β, TNFα, IL-6, and IL-2, are induced before Th2 cytokines TGFβ2, IL-10, and IL-4, although differences in the kinetics significantly affect the final response to infection." (PMID 39964091, 2025). "IL-10 is a cytokine with anti-inflammatory functions that restricts the inflammatory response to infection and minimizes tissue damage." (PMID 40563315, 2025).